ROCK1 (Rho associated coiled-coil containing protein kinase 1)
Diseases named in the same sentence as ROCK1 in open-access papers (continued):
Sharing a sentence is not in itself a finding about the gene and the disease.
vascular tumors (1 paper, 2017). "To address this, we performed immunohistochemistry to compare ROCK1 and 2 expression in normal vasculature, as well as benign, borderline, and malignant vascular tumors." (PMID 28709411, 2017). "In the current study, we examined the protein expression patterns of ROCK1 and 2 in a panel of diverse vascular tumors and subsequently employed a shRNA driven approach to elucidate the role of ROCK1 and 2 in a vascular tumor xenograft model." (PMID 28709411, 2017). "In this study, we compared ROCK1 and 2 protein expression in a large panel of benign and malignant vascular tumors to that of normal vasculature." (PMID 28709411, 2017). "Our data revealed that both ROCK1 and 2 protein levels were elevated across vascular tumors relative to normal endothelium." (PMID 28709411, 2017). "This suggests that ROCK1 and 2 proteins are upregulated across a broad range of vascular tumors and may serve as excellent therapeutic targets against these tumor types." (PMID 28709411, 2017). "Our animal studies revealed that knockdown of ROCK2, but not ROCK1, greatly reduced xenograft tumor volume in an established xenograft vascular tumor model." (PMID 28709411, 2017). "shRNA-mediated knockdown of ROCK2, but not ROCK1, in xenograft vascular tumors significantly reduced tumor size and proliferative index compared to control tumors." (PMID 28709411, 2017). "Given our data demonstrating that ROCK1 and 2 are expressed across benign, borderline, and malignant vascular tumors, we sought to test if reducing the activity of the ROCK proteins would disrupt vascular tumor progression in a xenograft tumor model." (PMID 28709411, 2017).
vitiligo (1 paper, 2022). Generalized well circumscribed patches of leukoderma that are generally distributed over symmetric body locations and is due to autoimmune destruction of melanocytes. "Another study also described a decrease in cell proliferation and initiation of apoptosis via caspase-3 and caspase-7 induction due to miR-145 overexpression in non-lesional skin of patients with vitiligo via targeting ROCK1, CAMK1D, and EIF2AK161,106." (PMID 35941163, 2022).
vulvar carcinoma (1 paper, 2014). "In this study, we examined the function of the Rho-associated protein kinase ROCK1 in human vulvar carcinoma." (PMID 25380619, 2014). "ROCK1 immunostaining was also associated with important clinical features in vulvar cancer and with the most significant clinical property and prognostic factor in this tumour: lymph node metastasis." (PMID 25380619, 2014). "Although the relationship between apoptosis and the prognosis remains unknown, it could, at least in part, explain the association of ROCK1 with a good prognosis in vulvar cancer." (PMID 25380619, 2014). "Nevertheless, vulvar carcinomas can be highly heterogeneous, and cytoplasmic immunostaining for ROCK1 protein was heterogeneous in all tumour extensions in our cases, reflecting a disadvantage of ROCK-targeting therapies in this tumour type." (PMID 25380619, 2014). "The transcript and protein results were correlated with clinicopathological characteristics to determine the prognostic value of ROCK1 in vulvar cancer." (PMID 25380619, 2014). "We aimed to examine the function of ROCK1 in the progression of vulvar carcinoma." (PMID 25380619, 2014). "Based on its involvement in cell migration in other tumours and the lack of data on its function in vulvar carcinomas, we selected ROCK1 for further study." (PMID 25380619, 2014). "Rho-associated coiled-coil-containing protein kinase 1 (ROCK1) has been implicated in many cellular processes, but its function in vulvar cancer has never been examined." (PMID 25380619, 2014).
vulvar squamous cell carcinoma (1 paper, 2014). An invasive squamous cell carcinoma arising from the vulva. "In this study, we aimed to determine the prognostic value of ROCK1 gene and protein analysis in vulvar squamous cell carcinoma (VSCC)." (PMID 25380619, 2014).
tumor (221 papers, 2011 to 2026). "For example, Rho-associated protein kinase (ROCK1) was enriched where a bone stroma was present and this has previously been found to be overexpressed in cell migration and invasion in neoplasms." (PMID 38226014, 2024). "miR-335-5p downregulation in NSCLC tumor tissue is associated with lymph node metastasis through the regulation of ROCK1." (PMID 35806142, 2022). "In this experiment, the tumor environment only caused increases in RhoA, ROCK1 and ROCK2, and other components of this signaling pathway were not elevated." (PMID 35811723, 2022). "Several somatic mutations in ROCK1 are present in human cancers, and all these mutations have enhanced kinase activity of ROCK1, as well as increased motility of tumor cells." (PMID 35179516, 2022). "It has been shown that Rho-associated protein kinase 1 (ROCK1) affects tumor development by regulating cellular processes, including proliferation, migration, invasion, apoptosis, and the EMT." (PMID 36619866, 2022). "ROCK1 is a member of the Rho‐associated protein kinase family and has a role in cell invasion in neoplasms." (PMID 32996285, 2020). "Rho-associated kinase 1 (ROCK1) regulates tumor metastasis by maintaining cellular cytoskeleton homeostasis." (PMID 32554853, 2020). "Higher ROCK1 expression levels were associated with tumor stage, and Gleason grade, positive nodal stage, positive surgical margin, accelerated cell proliferation and early PSA recurrence in multivariable analysis." (PMID 31557128, 2019). "Increased ROCK1 expression was significantly associated with advanced tumor stage, high classical and quantitative Gleason grade, positive nodal stage, positive surgical margin (p<0.0001 each), and high preoperative PSA level (p=0.0111)." (PMID 31557128, 2019). "Taken together, these findings demonstrated that lycorine inhibited tumor growth and induced apoptosis in a HepG2 xenograft mouse model in association with ROCK1 activation." (PMID 31263414, 2019). "Meanwhile, an in vivo study revealed that lycorine inhibited tumor growth and induced apoptosis in a HepG2 xenograft mouse model in association with ROCK1 activation." (PMID 31263414, 2019). "Previous studies by our group indicated that miR-335 functioned as a tumor suppressor by way of directly targeting to its downstream gene - Rho associated coiled-coil containing protein kinase 1 (ROCK1)." (PMID 29753317, 2018). "Recently, we found that angiogenic tumor pericytes exist in a synthetic, highly proliferative state but can be switched to a more mature (or contractile) phenotype by activating intrinsic Rho-associated coiled-coil forming kinase (ROCK1, RhoA kinase." (PMID 40140727, 2025). "The differences in functional outcomes of ROCK1 deficiency in MEFs vs. leukemic cells are likely due to variations in anchorage-dependency, cytoskeleton organization and interacting partners in normal vs. tumor cells." (PMID 35043239, 2022). "The ROCK1 signalling is also implicated in tumour cell infiltration and metastasis." (PMID 32776418, 2020). "ROCK1 was implicated in the metastasis and invasion of tumours." (PMID 32776418, 2020). "In addition, our in vivo studies revealed that lycorine significantly inhibited tumor growth in HepG2 xenografts in association with ROCK1 activation." (PMID 31263414, 2019). "Given that treatment with the ROCK inhibitor Y-27632 prevents anoikis, tumor cells harboring the ROCK1 nonsense mutation might be resistant to anoikis through the impairment of the Rho-ROCK pathway, similar to tumor cells harboring the RHOA L57V mutation." (PMID 26811494, 2016). "The ROCK1 gene codes for the Rho-associated, coiled coil containing protein kinase 1, which is a downstream effector of the Rho-pathway, that seems to play a role in tumor metastasis and invasion by influencing cell adhesion and migration capacity." (PMID 24504141, 2014).
tumor (continued). "Notably, the combined miR-340 downregulation and ROCK1 mRNA upregulation was significantly associated with the presence of tumor metastasis and the poor response to pre-operative chemotherapy." (PMID 24398981, 2014). "In addition, TNF-α, IL-6, and IL-1β release allows for tumor cell implantation and growth by increasing expression of adhesion proteins including E-selectin and upregulation of rho-associated protein kinase-1 (ROCK1), vascular endothelial growth factor (VEGF), and matrix metalloproteinases (MMPs)." (PMID 39682147, 2024). "Moreover, circHIPK3 sponged the tumor-suppressive miR-124 leading to an increased expression of miR-124 targets, including rho-associated protein kinase 1 (ROCK1) and CDK6, thereby showing the potential of circHIPK3 as a potential diagnostic marker and therapeutic target in GBC." (PMID 33614648, 2021). "Collectively, these data reveal that ARL5B drives lipid synthesis and tumor progression via ROCK1‐mediated activation of SREBP1, providing mechanistic insights into how metabolic alterations fuel ESCC aggressiveness." (PMID 41144804, 2026). "Pharmacological inhibition of ROCK1 with Y-27632 mitigated these effects, suppressing tumor growth, restoring apoptosis, and inducing cell cycle arrest." (PMID 40368918, 2025). "ROCK1, as a key node regulating tumour invasion and metastasis, its inhibitors (such as Fasudil) have shown potential in inhibiting the metastasis of various solid tumours." (PMID 40940984, 2025). "Surprisingly, in the presence of the ROCK1 inhibitor Y-27632, macrophages exhibited augmented phagocytic activity against tumor cells following radiation-induced ICD." (PMID 40368918, 2025). "Subsequently, we identified RhoA kinase (ROCK1) activity as a key determinant of tumor pericyte plasticity." (PMID 40140727, 2025). "Immunophenoscore analysis has unveiled that heightened ROCK1 expression correlates with increased tumor cellularity and diminished tumor-infiltrating immune cells, further underscoring the potential of ROCK1 as an adverse prognostic factor." (PMID 40368918, 2025). "Antioxidant 1 (ATOX1) copper chaperone and RhoA/Rho kinase 1 (ROCK1) are novel anti-tumour targets in cancers." (PMID 40940984, 2025). "Histopathological evaluation through HE staining and immunohistochemical profiling demonstrated that FBZ treatment induced extensive tumor necrosis while suppressing proliferative (Ki67) and metastatic (ROCK1) markers in xenograft tissues." (PMID 40509264, 2025). "circFECR1 sequesters and inactivates the tumor suppressor miR584-3p, activating the ROCK1 gene and driving metastasis." (PMID 41299506, 2025). "Another interesting observation here is the presence of signaling by the VEGF pathway, which involved two upregulated genes (KDR, VEGFA) and three downregulated genes (NRP1, PRKACB, ROCK1) in G2 tumor AOIs compared to G1." (PMID 39245631, 2025). "Studies have indicated that GSK269962A was a selective ROCK1 inhibitor, which can inhibit tumor growth." (PMID 40936936, 2025). "The putative mechanism involves the activation of the ROCK1/c‐Myc/PD‐L1 axis, allowing tumor cells to evade immune destruction, consequently diminishing the therapeutic efficacy of anti‐PD‐L1 antibodies." (PMID 39503247, 2024). "As proposed as a tumor suppressor, miR-136-5p functionally interacts with a variety of target genes, such as ROCK1 41, BCL2 42, or SMAD3 43, to interfere with cancer cell invasion and migration." (PMID 38495489, 2024). "Rho-associated protein kinase 1 (ROCK1) directly phosphorylates Smad5, enhancing vasculogenic mimicry and stemness in tumor cells." (PMID 39578779, 2024). "Because RhoA/ROCK1 signaling is also closely related to tumor EMT and metastasis, we further investigated the role of HIF‐1α in DDR1‐induced EMT and metastasis in GC." (PMID 39024501, 2024). "In both human and mouse KRAS-driven tumours, an increase in tumour progression correlates with elevated levels of ROCK1/ROCK2 kinases." (PMID 36175301, 2023).
tumor (continued). "ROCK1 plays an important role in regulating cell movement, angiogenesis and migration which can promote the growth, proliferation, survival of tumor cells by regulating the tumor microenvironment." (PMID 36781836, 2023). "Rho GTPases, a kind of regulator for intracellular actin dynamics, mainly consisting of RhoA, Rock1/2, Cdc42, and Rac1, can dramatically interfere with the motility of tumor cells." (PMID 36969843, 2023). "Reduced expression of miR-139 in OS has been identified as a tumor suppressor of tumorigenesis, and its suppressive effect on tumor cell proliferation and invasion has been demonstrated by targeting ROCK1." (PMID 37240338, 2023). "miR-124 targets many proteins like SCP1, Rho-associated protein kinase 1 (ROCK1), STAT3, matrix metallopeptidase 9 (MMP9), and inhibits tumor cell proliferation in GBM." (PMID 37508353, 2023). "Studies have shown that miR-miR-148a acts as a tumor suppressor at OS by targeting ROCK1 and exerting a suppressive effect on the proliferative, invasive, and migratory capabilities of Saos-2 and U2OS cells." (PMID 37240338, 2023). "We also calculated the variation in ROCK1 expression in each tumor at different clinical phases to assess the impact of ROCK1 on tumor progression and severity." (PMID 37683138, 2023). "ROCK1 serves an important function in cell migration and invasion in neoplasms, and is the classic downstream effector of the small GTPase RhoA, the activation of which is mediated by AKT phosphorylation." (PMID 37369706, 2023). "The trials revealed that HK2, ITGA5, and ROCK1 were positively expressed in the tumor (CESC and PANC-1) cell lines compared with the normal (HUCEC) cell lines." (PMID 36837559, 2023). "In contrast to miR-21, miR-126 acts as a tumor suppressor in tumor tissue, e.g., by targeting ROCK1 (Rho-Associated Coiled-Coil Containing Protein Kinase 1) and VEGFA (Vascular Endothelial Growth Factor A)." (PMID 37046643, 2023). "ROCK1 has the ability to drive cortical actomyosin contraction and is closely related to tumor metastasis." (PMID 36774349, 2023). "According to another study, HSN suppresses tumor development and promotes apoptosis in an A549 xenograft mouse model via the ROCK1/PTEN/PI3K/Akt/GSK3 signaling pathway." (PMID 37630393, 2023). "Here, the expression level of ROCK1 is higher in LSCC tissues than non-tumor tissues, and the expression level of ROCK1 is positively correlated with advanced stage and poor survival prognosis." (PMID 36197602, 2022). "In the present study, the expression level of ROCK1 is higher in LSCC tissues than non-tumor tissues, and the expression level of ROCK1 is positively correlated with advanced stage and poor survival prognosis." (PMID 36197602, 2022). "In PC, ROCK1 is highly expressed, and its inhibition decreased tumor cell growth and CAFs in a previous study." (PMID 36077069, 2022). "Our findings demonstrated that the knockdown of ROCK1 reversed the tumor-promoting effects of circCSPP1." (PMID 35101080, 2022). "Taken together, these findings demonstrated that the knockdown of ROCK1 reversed the tumor-promoting effects of circCSPP1." (PMID 35101080, 2022). "Meanwhile, it has been reported that ROCK1 promotes tumor cell migration and invasion through mechanisms independent of cytoskeleton remodeling, such as the upregulation of MMP-9." (PMID 35626071, 2022). "As previously reported in many studies, ROCK1 mainly regulates tumor metabolism in solid tumor cells whilst having an essential role in the growth and survival of AML cells." (PMID 36561342, 2022). "In other studies, ROCK1/2 have been shown to regulate actomyosin contractility and cytoskeleton assembly, important features for tumor progression, migration and invasion." (PMID 35365653, 2022). "For instance, upregulation of TUG1 facilitates tumor growth in laryngocarcinoma through targeting miR-145-5p/ROCK1 axis." (PMID 35601153, 2022).
tumor (continued). "ROCK1 is an essential effector kinase of Rho GTPases and plays a vital role in regulating tumor invasion and metastasis." (PMID 35997665, 2022). "circHIPK3 sponges the tumor-suppressive miR-124 leading to an increased expression of miR-124 targets, including ROCK1 (rho-associated protein kinase 1) and CDK6 (rho-associated protein kinase)." (PMID 35645336, 2022). "Circ-E2F3 as a tumor promoter promoted RB proliferation, metastasis, and apoptosis by modulating the miR-204-5p/ROCK1 axis." (PMID 35865469, 2022). "Conversely, lncRNA MORT is down-regulated in OSCC tumor tissues and inhibits tumor malignant phenotypes by regulating ROCK1." (PMID 35258410, 2022). "Previous studies indicate that ROCK1 is generally overexpressed in multiple types of cancers and enhances the migratory ability of tumor cells by actin polymerization." (PMID 35626071, 2022). "In 225 cases of PTC (128 cases with lymphatic metastasis and 97 cases without lymphatic metastasis), qRT–PCR analysis revealed that ROCK1 expression was significantly higher in tumor tissue than in normal adjacent tissue." (PMID 35379935, 2022). "ROCK1nc mice were previously shown to develop fewer HCC tumours than ROCK1wt mice, suggesting that tumour development was affected by the inability of tumour cells to cleave and thereby activate ROCK1." (PMID 36497425, 2022). "A MUC20 -lncRNA has been reported to bind ROCK1 and to be functionally involved in tumor suppression indicating trans-regulation." (PMID 34194481, 2021). "The expression of ki67 and ROCK1 was significantly suppressed in the tumor tissues formed by sh-SNHG20-transfected OC cells." (PMID 34836544, 2021). "The results revealed that ROCK1 expression was significantly higher in SCLC tissues than in non-tumor tissues (p < 0.05)." (PMID 34271873, 2021). "Consistent with these, our results demonstrate that ZnPc-PDT with 12 J/cm2 or 24 J/cm2 irradiation can inhibit the tumor migration and downregulate the expression of ROCK1 and MMP9 in SW480 cells." (PMID 34833970, 2021). "There was a negative relation (r = − 0.582, P = 0.004) between miR-493-5p and ROCK1 but a positive correlation (r = 0.621, P = 0.002) between circ_PIP5K1A and ROCK1 in tumor-resistant samples." (PMID 34537072, 2021). "The resulting elevation in ROCK1 expression drives LIMK1/Cofilin-1 signaling that promotes pro-tumor cellular behaviors." (PMID 33414429, 2021). "Next, we examined the expression of ROCK1 mRNA in PC tumor tissues and verified that ROCK1 was highly expressed in these tissues." (PMID 33414429, 2021). "ROCK1, as an effector of the small GTPase RhoA, is usually upregulated in different cancers and can increase cancer cell motility to promote tumor invasion and metastasis." (PMID 34271873, 2021). "Next, we tested ROCK1 inhibitor GSK269962 (2 mg/kg) in combination of murine DR5 agonist MD5‐1 (50 μg dose) in 4T1 syngeneic TNBC tumor models." (PMID 33587338, 2021). "In comparison to the parental cells and tumor-sensitive tissues, ROCK1 was upregulated (P < 0.001) in DDP-resistant cells and tumor-resistant tissues." (PMID 34537072, 2021). "Consistent with higher PD‐L1 in chi‐G4S‐DR5 stable 4T1 tumors, DR5 agonist and ROCK1 inhibitor co‐treatment (similar to MD5‐1‐ROCK1 co‐targeting) showed higher anti‐tumor efficacy (tumors isolated after seven doses) as compared to lexatumumab alone." (PMID 33587338, 2021). "Tumor cells having lower apoptotic threshold not only mobilized PD‐L1 on cell surface (both in vitro and in vivo) but also shuttle it to neighboring tumor cells in a process that requires ROCK1 activation." (PMID 33587338, 2021).